CA9 (carbonic anhydrase 9)
Diseases named in the same sentence as CA9 in open-access papers (continued):
Sharing a sentence is not in itself a finding about the gene and the disease.
cancer (continued). "Considering that CA9 is strongly upregulated in many cancers and no direct interaction of CA9 with peripheral blood cells has been reported so far, we decided to further explore this interaction." (PMID 39768175, 2024). "Although CA12 is not regulated by hypoxia, along with CA9, CA12 represents another membrane associated CA implicated in cancer development." (PMID 38530845, 2024). "Moreover, previous studies have implicated ACKR3, CHAF1B, CHEK1, and COL11A1 as being involved in cancer cell proliferation, while CA9, CHAF1B, and COL11A1 play roles in cancer invasion and migration." (PMID 38652547, 2024). "Since kidney cells, however, potentially express PDPN, we sought to identify a cancer cell line with CA9 but not PDPN under normoxic conditions as found in peripheral blood where platelets are predominantly found." (PMID 39768175, 2024). "Furthermore, in glycolytic cancer cells, PERK activity induces carbonic anhydrase 9 (CA9) and thus prevents cells acidosis." (PMID 37721642, 2023). "Furthermore, studies have revealed that exosomes released from hypoxic clear cell RCC cells contain carbonic anhydrase 9 (CA9), which enhances angiogenesis within the TME, consequently driving cancer progression." (PMID 37762660, 2023). "Cancer cells compete with immune cells for glucose uptake (by SLC2A1/GLUT1), produce lactic acid (by LDHA), and generate an acidic extracellular milieu (through the activity of CA9), all of which are immunosuppressive." (PMID 35499076, 2022). "Conversely, CA9,21, 22 has been reported to be elevated in BE/EAC and hypoxia in cancer." (PMID 35560527, 2022). "Our results suggest that, similar to CA9 and GLUT1, GLUT3 protein levels are elevated in hypoxic prostate epithelial cells and cancer lines and may serve as a reliable biomarker of hypoxia in tissue." (PMID 35328229, 2022). "Carbonic anhydrase 9 (CA9), as one of the CAs that play a crucial role in equilibrating the reaction between CO2, HCO3−, and H+, is inductively expressed during hypoxia in various cancers." (PMID 36230613, 2022). "The negative regulation of REG4 by GATA6 was reversed to be positive from normal to cancer, the positive regulation of CA9 by GATA6 in normal tissue disappeared in cancer and the negative regulation of STC1 by GATA6 in normal stage was also disappeared in cancer." (PMID 35421923, 2022). "Consistent with previous reports, CA9 staining was negative in the cytoplasmic of adjacent tissue cells; meanwhile, CA9 staining was strongly positive in the cancer tissue cells." (PMID 34878732, 2022). "ASS1 and ARG2 expression by cancer cells or by CAFs were not related to the expression of HIF1α, LDH5, or CA9 by cancer cells." (PMID 34344457, 2021). "Together, our findings suggest that Ndufa4l2 may play a fundamental role as a driver of ccRCC lipid accumulation and expression of CA9 and ENO1 cancer biomarkers." (PMID 34970493, 2021). "Despite pre-clinical data supporting the use of CA9 inhibition as a therapeutic option for cancers, there have not been any human studies demonstrating its benefit." (PMID 33007872, 2020). "CA9 is not detected in most normal tissues, but its expression in various cancers indicates hypoxic tumors and poor treatment response." (PMID 32024881, 2020). "Further on, exosomes containing carbonic anhydrase 9 (CA9), a cellular response to hypoxia, were released from hypoxic RCC cells, and they are suggested to enhance angiogenesis in the microenvironment, thereby contributing to cancer progression." (PMID 32379831, 2020). "The variability in CA9 expression observed in our in vitro and in vivo studies further supports the proposal that CA9 should not be used as a hypoxia marker during a cancer diagnosis." (PMID 31142270, 2019).
cancer (continued). "Among the commonly upregulated LD+ associated genes in GBM cells and patient tumors, we found several hypoxia-related, key effectors of angiogenesis, macrophage recruitment and stromal remodeling in cancer (e.g. VEGF-A, TGF-β1, IL1β, ADM, IGFB3, LOX, CA9, THBS1, PLODs, ID2)." (PMID 31174567, 2019). "Of the CA isoforms, only CA9 and CA12 are highly expressed in cancer tissues and therefore may contribute to the acidification of the extracellular milieu." (PMID 30863491, 2019). "In the younger group, CA9 expression was significantly higher in fusion-positive cancers than in fusion-negative cancers (P = 0.042)." (PMID 30034621, 2018). "The CA9-model correctly classified 139 of 144 samples independent of cancer stage (ACC = 96.5%, ROC AUC = 0.98)." (PMID 26901863, 2016). "To complement these data, we investigated the effects of docetaxel on the expression of HIF-1α target genes (Glut1, CA9, LDHA, and BNIP3) involved in the metabolism of cancer cells and pro-apoptotic genes (CASP3, CASP8, and CASP10) in siJNK2-transfected MDA-MB-231 cells under hypoxic conditions." (PMID 27263528, 2016). "Olaparib alone increased apoptosis rate in CA9-positive cells (P<.05), and when in combination with radiation, apoptosis was significantly enhanced in CA9-positive cells (P<.001), but not in CA9-negative cancer cells, compared with radiation alone." (PMID 27020103, 2016). "CA9 expression is strongly induced by hypoxia-inducible factor 1 (HIF-1) and is believed to be involved in cancer cell proliferation, transformation and survival, making it a potential target for cancer therapy." (PMID 25890268, 2015). "For that reasons, we decided to focus on CA9 as the major effective target of TBZT against cancer although we do not exclude the involvement of other isozymes." (PMID 22748168, 2012). "CA9 positive non-basal cancers had higher numbers of Treg (median Treg = 21 per 1 mm core, n = 32) compared to CA9 negative non-basal cancers (median Treg = 8 per 1 mm core, n = 21) (Mann-Whitney U P = 0.044)." (PMID 21521526, 2011). "The organization of the Ca9 promoter with the HRE immediately upstream of the transcription start enables tight regulation by HIF-1 and suggests that Ca9 would be an excellent hypoxic marker in cancers." (PMID 21966417, 2011). "The mean percentage of cells positive for CA9 was not statistically significantly different in primary and secondary cancers (14.0 vs 10.7, respectively, P=0.27)." (PMID 21540863, 2011). "Cancer cells adapt to hypoxia by modulating the expression of genes involved in neoangiogenesis (e.g., vascular endothelial growth factor, VEGF), glucose uptake (e.g., glucose transporter, GLUT1), pH modulation (e.g., carbonic anhydrase IX, CA9), and other adaptive mechanisms." (PMID 38928200, 2024). "We successfully prepared a new Cu(ii)-BODIPY PS complex (CA9-BPS-Cu(ii)) containing a CA9-targeting ligand, acetazolamide, and demonstrated its efficacy in promoting a synergistic CDT/PDT effect with CSC targeting to enhance cancer therapy in vitro and in vivo." (PMID 36819853, 2023). "Their in vitro results, based on migration and tube formation assays, suggested the possibility that carbonic anhydrase 9 (CA9) enriched in exosomes and released from hypoxic RCC may enhance angiogenesis in the microenvironment, thereby contributing to cancer progression." (PMID 37372161, 2023). "Among these proteins, AXL receptor tyrosine kinase (AXL), carbonic anhydrase IX (CA9), enolase 2 (ENO2), human epidermal growth factor receptor (HER) 1, HER2, HER3, progranulin (PRGN), and platelet-derived growth factor-AA (PDGF-AA) are primarily involved in cancer cell proliferation." (PMID 35745691, 2022). "Although the inhibition of CA9 did not affect the basal level of glycolysis, it significantly inhibited the gemcitabine-induced acceleration of extracellular acidification and mitochondrial functions in cancer cells, which was verified in xenografted mice." (PMID 36578477, 2022).
cancer (continued). "The sCA9 levels were correlated with tissue CA9 expressions in CRC patients (p < 0.05), considering that detection of sCA9 may be used to reflect the levels of CA9 in tumors as a reference during cancer therapy." (PMID 26447758, 2015). "In addition, the recently observed overexpression of carbonic anhydrase IX (CAIX; CA9) in basal-like carcinomas supports what has long been suspected, that tumors of this subtype activate a hypoxic response to survive under conditions of rapid and aggressive growth." (PMID 24281106, 2010). "Furthermore, CA9 expression is mainly found in high-grade, steroid receptor negative cancer tissues." (PMID 12865916, 2003). "CA9 expression was mainly found in high-grade, steroid receptor negative cancer tissues." (PMID 12865916, 2003). "Therefore, CA9 should not be used as a hypoxia marker in all cancer cell lines." (PMID 31142270, 2019).
adenocarcinoma (25 papers, 2008 to 2025). A common cancer characterized by the presence of malignant glandular cells. "Interfering with pH regulation in LS174Tr (adenocarcinoma) spheroids by silencing of CA9 gene (LS-shCA9/ctl) reduced proliferation and the growth was further reduced when both CA9 and CA12 genes (LS-shCA9/CA12−) were silenced." (PMID 31810330, 2019).
infection (5 papers, 2011 to 2024). The state of being infected such as from the introduction of a foreign agent such as serum, vaccine, antigenic substance or organism. "These analyses combined with our data from primary infection and transformed B-lymphocytes models indicated CA9 might be the only prominent membrane associated CA isoform expressed in B-lymphocytes in response to EBV infection." (PMID 38530845, 2024). "Collectively, these data suggest that EBV infection alters CA9 expression and its activity during the early infection stages to support the significant physiological shift from quiescence to rapid lymphoblastic proliferation." (PMID 38530845, 2024). "The infection of several cell lines with NDV inhibits HIF-1α protein accumulation and, consequently, decreases the transcription of the HIF-1α target genes, particularly the carbonic anhydrase 9 gene, which encodes the CAIX protein." (PMID 33135539, 2020). "EBNA2 recruitment onto CA9 promoter/ enhancer region further prompted us to examine whether loss of EBNA2 gene expression abrogates CA9 expression and its activities during EBV initial phase of infection of primary B-lymphocytes." (PMID 38530845, 2024). "EBV induced transcriptional activation of CA9 and CA12 expressions during early stage of infection of naïve B-lymphocytes prompted us to further profile CA expressions in transformed B-lymphocytes." (PMID 38530845, 2024). "O group Vpus from Ca9 and BCF06 are thus able to disrupt the TGN, which is likely to impact on cell function and viability, although the implications of this observation during natural infection remain unclear." (PMID 21900423, 2011).
neurodegenerative disease (3 papers, 2012 to 2025). A disorder of the central nervous system characterized by gradual and progressive loss of neural tissue and neurologic function. "The newly developed CRISPR/Ca9 technology will promote the generation of non-human primates and large animal models of neurodegenerative diseases and enhance our understanding of the pathogenesis of these important diseases." (PMID 26238861, 2015).
hematological cancers (2 papers, 2022 to 2024). "Continuous CA9-expression is an indicator of poor prognosis not only in solid tumors but also in hematological cancers." (PMID 36415514, 2022). "While CA9’s role in regulating cellular pH balance in solid tumors is well described, we hypothesize a different function for hematological cancer, potentially related to CLEC2 interaction." (PMID 39768175, 2024).
CA9 also shares sentences with these, for which no sentence is quoted: renal tumors (9 papers); nasopharyngeal carcinoma (7); adenoma (5); colorectal (5); head and neck tumors (5); osteosarcoma (5); benign tumors (4); cervical dysplasia (4); cyst (4); genitourinary cancers (4); glaucoma (4); laryngeal carcinoma (4); urothelial carcinoma (4); adrenocortical cancer (3); atherosclerosis (3); cardiovascular diseases (3); COVID-19 (3); epilepsy (3); hemangioblastoma (3); oligodendroglioma (3); papillary renal cell carcinoma (3); pheochromocytoma (3); preeclampsia (3); adrenocortical tumor (2); anaplastic astrocytoma (2); anaplastic thyroid cancer (2); basal cell carcinoma (2); bladder urothelial cancer (2); carcinoid (2); cervical (2).
A further 135 diseases each share a sentence with CA9 in 2 papers or fewer.